CMC1 (C-X9-C motif containing 1)
Description:
Component of the MITRAC (mitochondrial translation regulation assembly intermediate of cytochrome c oxidase complex) complex, that regulates cytochrome c oxidase assembly.
Synonyms: Cmc1p; C3orf68; MGC61571
Tractability: PROTAC: ubiquitination databases record sites on it; its protein half-life has been measured.
Gene: Protein-coding gene on chromosome 3 (28,241,584 to 28,325,142, forward strand). Ensembl gene ENSG00000187118.
Subcellular location: Mitochondrion
Pathways (Reactome):
Metabolism: Complex IV assembly
Gene Ontology:
Molecular function: protein folding chaperone
Biological process: mitochondrial respiratory chain complex IV assembly; protein folding
Cellular component: mitochondrial intermembrane space; mitochondrion; mitochondrial matrix
Genetic constraint (gnomAD): Loss-of-function variants: 2 observed, 1.65 expected, observed/expected ratio (o/e) 1.21, 90% interval 0.41 to 1.91. That is too few expected variants to judge how well the gene tolerates losing a copy. Missense variants: 18 observed, 20.11 expected, observed/expected ratio (o/e) 0.9, 90% interval 0.62 to 1.33. Synonymous variants: 14 observed, 8.93 expected, observed/expected ratio (o/e) 1.57, 90% interval 1 to 1.94.
Homologues: Orthologues: chimpanzee CMC1 (99% identical), rabbit CMC1 (97% identical), macaque CMC1 (95% identical), guinea pig CMC1 (94% identical), pig CMC1 (94% identical), dog CMC1 (93% identical), mouse Cmc1 (89% identical), rat Cmc1 (83% identical), tropical clawed frog cmc1 (71% identical).
Diseases named in the same sentence as CMC1 in open-access papers:
CMC1 is named in the same sentence as 10 diseases in open-access papers, as found by Europe PMC text mining. Sharing a sentence is not in itself a finding about the gene and the disease. The quoted sentences say what the papers report.
glioma (2 papers, 2023 to 2024). A benign or malignant brain and spinal cord tumor that arises from glial cells (astrocytes, oligodendrocytes, ependymal cells). "CMC1, COX20, and UQCRB are other mitochondrial genes specifically involved in the prognosis of glioma." (PMID 39012280, 2024). "In conclusion, the three mitochondria-related signatures by UQCRB, CMC1, and COX20 have the ability to predict OS in gliomas." (PMID 37091853, 2023).
multiple myeloma (1 paper, 2025). "In particular, RGS‐1, DUSP2, and CMC1 are associated with immunosuppression and exhaustion as shown in CD8+ T cells of patients with rapidly progressive multiple myeloma." (PMID 39777847, 2025).
infection (3 papers, 2016 to 2025). The state of being infected such as from the introduction of a foreign agent such as serum, vaccine, antigenic substance or organism. "In patients with poor outcome and infection, PSME1, MTREX, and H2B1C were more abundant in T cell-derived EVs; COHA1 was less abundant in B cell-derived EVs; and PCSK9 and CMC1 were less abundant in the monocyte-derived EVs." (PMID 41345658, 2025). "In addition, among 46 TRP32 target genes previously found to be differentially expressed during infection, 8 are also TRP47 targets, including CAP1, CMC1, HLX, ING1, MTFR2, NAT10, PARP16, and POLDIP3." (PMID 30408047, 2018).
tumor (1 paper, 2022). "Moreover, the result of Western blots showed that the expressions of SDHB and CCS were downregulated and that of ULK1, CDKN2A, and CMC1 were upregulated in tumor tissues compared with normal tissues." (PMID 36505872, 2022).
CMC1 also shares sentences with these, for which no sentence is quoted: autoimmune disease (1 paper); bladder cancer (1); cancer (1); celiac disease (1); liver fibrosis (1); transverse myelitis (1).